CYP1A2 (cytochrome P450 family 1 subfamily A member 2)
Diseases named in the same sentence as CYP1A2 in open-access papers (continued):
Sharing a sentence is not in itself a finding about the gene and the disease.
colorectal cancer (12 papers, 2007 to 2025). A primary or metastatic malignant neoplasm that affects the colon or rectum. "We noticed that 3 previous meta-analysis had been reported on the colorectal cancer risk with CYP1A2*F, CYP1B1 Leu432Val, and Asn453Ser polymorphisms." (PMID 25115775, 2014). "Cafestol and kahweol may lower colorectal cancer risk by reducing bile acid synthesis and secretion, and inhibiting the activity of CYP1A2 and NAT2." (PMID 27078843, 2017). "Cytochrome P450 1A2 (CYP1A2) encodes a member of the cytochrome P450 superfamily of enzymes, which play a central role in activating and detoxifying many carcinogens and endogenous compounds thought to be involved in the development of colorectal cancer (CRC)." (PMID 23951174, 2013). "A study with commercial herbal supplement FastOneTM showed an increase of both EROD activity and protein level of CYP1A2, and thus suggests that intake of the herbal supplement may increase the risk of colorectal cancer in humans with the rapid NAT2 phenotype." (PMID 21217855, 2009). "A number of epidemiological studies have evaluated the association between CYP1A2*F, CYP1B1 Leu432Val, Asn453Ser, and Arg48Gly polymorphisms and colorectal cancer risk, but the results remain inconclusive." (PMID 25115775, 2014). "The purpose of this study is to evaluate the role of CYP1A2*F, CYP1B1 Leu432Val, Asn453Ser, and Arg48Gly genotypes in colorectal cancer susceptibility." (PMID 25115775, 2014). "To date, a number of molecular epidemiological studies have been done to evaluate the association between CYP1A2*F, CYP1B1 Leu432Val, Asn453Ser, and Arg48Gly polymorphisms and colorectal cancer risk in diverse populations." (PMID 25115775, 2014). "The previous published data on the association between CYP1A2*F (rs762551), CYP1B1 Leu432Val (rs1056836), Asn453Ser (rs180040), and Arg48Gly (rs10012) polymorphisms and colorectal cancer risk remained controversial." (PMID 25115775, 2014). "Our objective was to measure the interactions between common polymorphisms of P450 (CYP1A2, CYP1B1, CYP2E1), GSTM1 and T1, SULT1A1 and cigarette smoking in colorectal cancer (CRC)." (PMID 17603900, 2007). "Results of meta-analysis for CYP1A2 and CYP1B1 polymorphisms on colorectal cancer risk." (PMID 25115775, 2014). "Therefore, we performed a comprehensive meta-analysis by including the most recent and relevant articles to identify statistical evidence of the association between CYP1A2*F, CYP1B1 Leu432Val, Asn453Ser, and Arg48Gly polymorphisms and risk of colorectal cancer that have been investigated." (PMID 25115775, 2014). "Moreover, further studies estimating the effect of gene–gene and gene–environment interactions may eventually lead to our better, comprehensive understanding of the association between the CYP1A2*F, CYP1B1 Leu432Val, Asn453Ser, and Arg48Gly polymorphisms and colorectal cancer risk." (PMID 25115775, 2014). "The present study identified six hub targets—GOT1, CYP2C9, CYP34, CYP1A2, CA2, and ABAT—that are involved in five core pathways related to HQD’s effects on malignant progression in colorectal cancer liver metastases, integrating transcriptomic and metabolomic analyses." (PMID 40732339, 2025). "The results of our meta-analysis supported the negative association between CYP1A2*F, CYP1B1 Leu432Val, Asn453Ser, and Arg48Gly polymorphisms and colorectal cancer risk." (PMID 25115775, 2014). "In summary, this meta-analysis indicates that CYP1A2*F, CYP1B1 Leu432Val, Asn453Ser, and Arg48Gly polymorphisms do not support an association with colorectal cancer, and further studies are needed to investigate the association." (PMID 25115775, 2014).
colorectal cancer (continued). "Although Hutu-80 cells are derived from the small intestine, unlike in the large intestine cancer-derived cell lines, the expressions of CYP1A1, CYP1A2, CYP2C9/10, and CYP3A could not be detected also in Hutu-80 cells." (PMID 34604364, 2021).
depression (12 papers, 2014 to 2025). "Two depression cohorts were investigated for the association between serum concentration and treatment response of mirtazapine and CYP1A2-163C>A (rs762551) and -3860G>A (rs2069514) genotype groups, also considering smoking status, sex, and age of the patients." (PMID 40353511, 2025). "The CAI values of the genes associated with depression displayed values ranging from 0.713 (UGT2B15) to 0.85 (CYP1A2)." (PMID 38346990, 2024). "Hence, it can be speculated that the CAI value 0.85 (CYP1A2 gene), in our depression study, likely also is associated with a high-level expression." (PMID 38346990, 2024). "Among approved drugs, the substrates for CYP1A2 include amitriptyline (anti-depression) and erlotinib (anticancer)." (PMID 26683337, 2015). "Cyclobenzaprine, a medication that creates a high anticholinergic burden, can exacerbate depression, and could be contributing to CYP1A2, CYP2D6, and CYP3A4 overload." (PMID 34063850, 2021). "According to the pharmacokinetic parameters, SNS had moderate inhibitory effects in the reserpine-induced depression model on CYP1A2, CYP2D1, CYP2E1, and CYP3A2, but no significant metabolic changes to CYP2C6 and CYP2D2." (PMID 32009949, 2019). "It was found that SNS may up-regulate CYP1A2, CYP2D1, CYP2E1, and CYP3A2 activity to reduce IL-6 and TNF-α expression, as well as up-regulation of BDNF and its receptor TrkB, reduce IL-1β, IL-6, and TNF-α expression to treat depression." (PMID 32009949, 2019).
Cirrhosis (11 papers, 2013 to 2025). A chronic disorder of the liver in which liver tissue becomes scarred and is partially replaced by regenerative nodules and fibrotic tissue resulting in loss of liver function. "A study of chronic HBV infection-induced fibrosis and cirrhosis patients showed that its therapeutic efficacy is closely related to the GA plus AA polymorphism of CYP1A2." (PMID 25897319, 2015). "In this study, 11 pairs of highly correlated genes and a panel of genes (cyp1a2-cyp2c19-il6) were identified in the core OAMs throughout the progression of CHB to cirrhosis and HCC." (PMID 33757544, 2021). "On the contrary, the results of qPCR and Western blot analyses show a markedly reduced increase in the mRNA level and protein expression of CYP1A1 and CYP1A2 in ascitic rats, indicating that induction is greatly curtailed in decompensated cirrhosis." (PMID 23626760, 2013). "Formation of phase I metabolites and clearance of the parent compounds were surprisingly robust in cirrhosis, although the phase I enzymes critical for the metabolism of the administered drugs in healthy mice, Cyp1a2 and Cyp2c29, were downregulated in cirrhotic livers." (PMID 38053838, 2023). "Several previous studies reported that the activities of several CYPs, including CYP1A2, CYP2A6, CYP2D6, CYP2C19, CYP2E1, and CYP3A were decreased in cirrhosis patients relative to healthy subjects." (PMID 27203676, 2016). "Compared with controls, the Km values of CYP1A2, CYP2A6, CYP2B6, CYP2C8, CYP2C19, CYP2E1, and CYP3A4/5 were higher in both in fibrosis and cirrhosis groups." (PMID 27203676, 2016). "In terms of Vmax, CYP2A6, CYP2B6, CYP2C9, CYP2D6, CYP2E1, and CYP3A4/5 were increased, while the Vmax values of CYP1A2 and CYP2C8 were decreased in both the cirrhosis and fibrosis groups compared to control subjects." (PMID 27203676, 2016). "Furthermore, the liver tissues of patients with liver failure and hepatic cirrhosis exhibited downregulated expression of CBS, CYP1A2, FOXA1, GSTZ1, WDR72 and UHMK1 when compared to healthy controls." (PMID 38287425, 2024).
lung carcinoma (11 papers, 2002 to 2024). "CYP1A2 plays a key role in bioactivating inhaled environmental or tobacco smoke procarcinogens increasing susceptibility to lung cancer." (PMID 32581794, 2020). "Several meta-analyses showed that the polymorphism 164A>C in CYP1A2 gene can result in 2–3 fold increase in the CYP1A2 activity, which has been associated with increased cancer risk, primarily lung cancer in Caucasians." (PMID 28404946, 2017). "Three studies reported a genetic association between CYP1A2 and lung cancer." (PMID 39457450, 2024). "However, it is possible that smoking behavior is the primary cause of lung cancer, with genetic mutations in CYP1A2 and CYP2A6 being secondary factors in its development." (PMID 39457450, 2024). "Moreover, induction of CYP1A2 is implicated in colon and lung cancers." (PMID 27800121, 2016). "Currently, there are very few studies elucidating the role of CYP1A2 as an AA epoxygenase in cancer development or progression, however, it remains possible that the formation of the pro-angiogenic EETs by CYP1A2 can play a role in lung cancer progression." (PMID 32581794, 2020). "The cumulative number of variants from CYP1A1 and CYP1A2 was in fact associated with a significant risk for lung cancer in ever smokers and a protective effect in never smokers, with a highly significant smoking-genotype interaction." (PMID 19479063, 2009). "Whether CYP1A2 and CYP2A6 are genetically linked to lung cancer in nonsmokers remains unclear." (PMID 39457450, 2024).
Obesity (11 papers, 2020 to 2025). Accumulation of substantial excess body fat. "The table below shows the frequencies and shares of the sample subjects according to gender, cups of coffee consumed, CYP1A2 rs762551 genotype, and the presence of obesity." (PMID 39063971, 2024). "Similarly, CYP1A2 expression has not been linked with obesity (p > 0.1)." (PMID 35745668, 2022). "The effect of CYP1A2 and CYP3A4 expressions on development of obesity was investigated in two separate logistic regression models (for the two levels of obesity) with clozapine dose and treatment duration as covariates." (PMID 33277605, 2020). "On one hand, the increased activity of cytochrome P450 (CYPs) (CYP2C9, CYP1A2, CYP2E1, and CYP2D6) in individuals with obesity could augment generation of toxic metabolites." (PMID 34040524, 2021). "All were non-smokers and had BMIs <26, so expected relationships such as smoking inducing CYP1A2 activity or obesity inhibiting CYP activity could not be assessed." (PMID 38370474, 2024).
diabetes (10 papers, 2014 to 2023). "Moreover, CYP1A2 activity has also been linked to type 2 diabetes mellitus and has demonstrated interaction effects with coffee consumption and BRCA1 mutation." (PMID 36581893, 2022). "A high-fat diet has been shown to significantly increase CYP1A2, 2E1, 2C, and 4A enzyme activities in streptozotocin-induced diabetes in Sprague–Dawley rats." (PMID 37034183, 2023). "In the diabetes group, we found a larger proportion of participants with the highly inducible CYP1A2 genotype." (PMID 27713762, 2016). "This is because caffeine is a known inducer of CYP1A2 activity, and the diabetes patients of the present study consumed larger amounts of caffeine." (PMID 27713762, 2016). "They found that diabetes patients showed higher activity of CYP1A2 than control groups." (PMID 32290519, 2020). "Moreover, a related study on CYP450 activities proved that the activity of CYP1A2 is slightly increased in the subjects with diabetes." (PMID 32814585, 2020). "CYP1A2 and CYP2C9 activities showed a trend to slightly increase in subjects with diabetes, but activities of CYP2D6 and CYP2E1 were unaltered." (PMID 32290519, 2020). "Growing evidence has demonstrated that diabetes increases the expression of some CYP450s (such as CYP2A1, CYP1A2, CYP2B1/2, CYP2C6, CYP2C7, CYP3A1/2 and CYP2E1) in rats, although opposite reports have also been shown." (PMID 32290519, 2020). "Hon inhibited the activity of CYP1A2 and CYP2E1 of diabetic rats dosage-dependently indicating that Hon could inhibit the activation of some pre-cancerogenic and toxic substances induced by diabetes, which had protective effect on body." (PMID 29534510, 2018).
type 2 diabetes (10 papers, 2016 to 2024). "Here, we provide evidence that a positive association between caffeine consumption and CYP1A2 activity is present in our type-2 diabetes patient sample." (PMID 27713762, 2016). "The -163C > A allele frequencies of the CYP1A2 gene were similar in type-2 diabetes and non-type-2 diabetes groups." (PMID 27713762, 2016). "CYP1A2 is involved in the metabolism of caffeine and has been reported in type 2 diabetes patients on caffeine therapy and/or consumes coffee." (PMID 29449808, 2018). "Estimated CYP1A2 enzyme activity, and thus speed of caffeine metabolism, was higher in our type-2 diabetes group; this was possibly due to higher intake of caffeine, a known inducer of CYP1A2 enzyme activity." (PMID 27713762, 2016). "Nevertheless, larger samples are needed in future studies to corroborate the existence of higher CYP1A2 activity in the type-2 diabetes patient population, and that this higher activity is due primarily to high caffeine intake." (PMID 27713762, 2016). "Since caffeine is almost completely metabolized by CYP1A2, this faster enzyme activity indicates a faster metabolism of caffeine in the type-2 diabetes participants." (PMID 27713762, 2016). "By contrast, the paraxanthine concentration was higher in the type-2 diabetes participants, consistent with our conclusion that CYP1A2 activity was higher in the patients than in the controls." (PMID 27713762, 2016). "The two selected predictors of CYP1A2 enzyme activity, i.e., type-2 diabetes status and higher caffeine intake, significantly predicted the paraxanthine/caffeine ratio (F2,200 = 5.580, p = 0.004)." (PMID 27713762, 2016). "In support of our hypothesis, the main finding of this field study was that CYP1A2 enzyme activity was significantly higher in a type-2 diabetes group compared to a control group." (PMID 27713762, 2016). "Hence, the present study aims to characterize the activity of CYP1A2, CYP2B6, CYP2C9, CYP2C19, CYP2D6, CYP3A4/5, and P-glycoprotein (P-gp) pump in patients with type 2 diabetes (T2DM)." (PMID 32337164, 2020). "Within the type-2 diabetes sample, patients who reported habitually consuming more caffeine than the population average showed a numerically faster CYP1A2 activity (0.763 vs. 0.638), but not to a significant degree (p = 0.276)." (PMID 27713762, 2016). "To estimate CYP1A2 enzyme activity, an established marker of caffeine metabolism, we quantified the paraxanthine/caffeine concentration ratio in saliva in 57 type-2 diabetes and 146 non-type-2 diabetes participants in a case–control field study." (PMID 27713762, 2016).
bladder cancer (9 papers, 2015 to 2026). "Genetic polymorphisms in detoxification enzymes such as NAT2 and CYP1A2 were shown to modify bladder cancer and NHL risk in susceptible individuals." (PMID 41399670, 2026). "Dysregulated CYP1A2 expression has been associated with the onset of various human cancers, including hepatocellular carcinoma, breast cancer, prostate cancer, bladder cancer, and endometrial tumors." (PMID 39039510, 2024). "Numerous studies have reported a link between CYP1A2 polymorphisms and the risk of bladder cancer (BLCA) to date." (PMID 39039510, 2024). "Previous research has explored the association between CYP1A2 polymorphisms and the risk of bladder cancer, with varying outcomes." (PMID 39039510, 2024). "An increasing number of SNPs have been linked to bladder cancer, and functional polymorphisms within the CYP1A2 gene have been identified as modulators of its activity, with implications for cancer susceptibility at various anatomical sites." (PMID 39039510, 2024). "To date, there has been a significant paucity of prior studies specifically investigating the potential correlation between variations in the CYP1A2 gene and susceptibility to bladder cancer." (PMID 39039510, 2024). "The study explored the association between bladder cancer and specific variants in the CYP1A2 gene (-163 C/A and − 3860G/A) among 170 patients, including 102 with low-grade tumors and 68 with high-grade tumors." (PMID 39039510, 2024). "Studies investigating the relationship between CYP1A2 polymorphisms and susceptibility to bladder cancer have yielded divergent results." (PMID 39039510, 2024). "In conclusion, this investigation sheds light on a robust association between CYP1A2 gene polymorphisms, particularly the − 163 C/A allele, and an increased susceptibility to bladder cancer (BLCA)." (PMID 39039510, 2024). "Specifically, prior investigations have examined the connection between CYP1A2-163 C/A and − 3860 G/A polymorphisms and susceptibility to bladder carcinoma." (PMID 39039510, 2024). "CYP1A2 activity is associated with increased risk of bladder cancer due to its role in bioactivating arylamines in cigarette smoke but the role of CYP1A2 epoxygenase activity has not been studied." (PMID 32581794, 2020). "Therefore, the current study was initiated with the primary aim of examining the potential impact of genetic variants within the CYP1A2 gene, specifically rs762551 and rs2069514, on an individual’s vulnerability to bladder cancer." (PMID 39039510, 2024). "The comparison between tumor and normal tissues revealed a significant elevation of CYP1A2 in tumor tissues, with p-values below 0.05, reaffirming its role in bladder cancer development." (PMID 39039510, 2024). "Haplotype 3 (G/G): The third haplotype, defined by the G/G genotype of the SNP CYP1A2.3860.G.A, was found in 86 individuals (50.6%) in bladder cancer patients and 109 individuals (64.1%) in the control group in the codominant model." (PMID 39039510, 2024). "Data from the TCGA revealed that CYP1A2 expression is significantly elevated in tumor tissues compared to normal tissues, highlighting its potential role in bladder cancer development and its promise as a therapeutic target." (PMID 39039510, 2024). "An essential enzyme in the pathophysiology of bladder cancer, CYP1A2 is involved in the activation of the two main known bladder carcinogens, aromatic amines (AAs) and polycyclic aromatic hydrocarbons (PAHs)." (PMID 39039510, 2024). "Haplotype 4 (G/A): The fourth haplotype, represented by the G/A genotype of the SNP CYP1A2.3860.G.A, was present in 72 individuals (42.4%) in the bladder cancer patients and 55 individuals (32.4%) in the control group in the codominant model." (PMID 39039510, 2024). "Specifically, survival analysis showed that higher CYP1A2 expression is significantly associated with better survival rates in non-smokers and women with early-stage bladder cancer, supported by p-values of less than 0.05." (PMID 39039510, 2024).
bladder cancer (continued). "The varying levels of CYP1A2 expression during bladder cancer progression suggest it could serve as a valuable biomarker." (PMID 39039510, 2024). "Higher expression levels of CYP1A2 were associated with improved survival rates, particularly in non-smokers and women with early-stage bladder cancer." (PMID 39039510, 2024). "Similarly, PHD use was associated with a 2.5-fold increased bladder cancer risk among women with the slow CYP1A2 genotype, an association not observed in the rapid genotype." (PMID 41399670, 2026).